PLS3 (plastin 3)
Diseases named in the same sentence as PLS3 in open-access papers (continued):
Sharing a sentence is not in itself a finding about the gene and the disease.
osteoporosis (continued). "This study focuses primarily on pathogenic or rare suspicious variants in low-density lipoprotein receptor-related protein 5 (LRP5), plastin 3 (PLS3), or proto-oncogene Wnt-1 (WNT1) as monogenic causes of osteoporosis." (PMID 37277619, 2023). "In contrast to osteoporosis and OI, studies have found increased levels of PLS3 in chondrocytes of patients with OA." (PMID 37484945, 2023). "The pathogenic mechanisms of early-onset osteoporosis caused by WNT1 and PLS3 mutations are incompletely understood and diagnostic biomarkers of these disorders are limited." (PMID 36157448, 2022). "The mouse knockout model for PLS3 showed decreased bone strength and osteoporosis, while PLS3 knockdown in zebrafish manifests in muscular and skeletal abnormalities." (PMID 34946798, 2021). "PLS3 osteoporosis was first described in 2013 as mutations in the X-chromosomal PLS3, encoding Plastin 3 (PLS3), were recognized to lead to severe childhood-onset osteoporosis." (PMID 32655496, 2020). "A Pls3 knock down in zebrafish manifests in significant skeletal and muscular abnormalities, while Pls3 knock out mice show significant osteoporosis and decreased bone strength mirroring human OI symptoms." (PMID 33553175, 2020). "Recently, some patients with PLS3 deletions have been described, and apart from severe osteoporosis there is a bone mineralization defect." (PMID 30042735, 2018). "More recently, the study of subjects with extreme phenotypes of osteoporosis, such as idiopathic juvenile osteoporosis and pregnancy-associated osteoporosis has yielded WNT1 and PLS3 as novel regulators of bone strength." (PMID 27533615, 2016). "Since relatively few families with PLS3 mutations have so far been described in the literature, the features and genetic variants of PLS3-related osteoporosis have not been fully characterized." (PMID 38043102, 2024). "A recent study showed that ubiquitous Pls3 KO in mice results in osteoporosis." (PMID 38549711, 2024). "Our report expands the genetic spectrum of PLS3-related osteoporosis." (PMID 38043102, 2024). "Female patients with expression of heterozygous genomic variants in X-Linked PLS3, MBTPS2 and SMS may have symptomatic osteoporosis." (PMID 38942908, 2024). "The clinical, radiographic and bone densitometry patterns, however, may overlap with Osteogenesis Imperfecta type 5 and familial forms of osteoporosis, such as heterozygous LRP5 variants and hemizygous PLS3 variants." (PMID 38942908, 2024). "Altogether, our results show that actin-bundling by PLS3 is part of the mechanosensitive mechanism that promotes osteoblast mineralization and thus begins to elucidate how PLS3 contributes to the development of bone defects such as osteoporosis." (PMID 38089885, 2023). "Since LRP5, PLS3, and WNT1 pathogenic variants cause osteoporosis, this was expected." (PMID 37277619, 2023). "To date, a strong correlation has been established between early onset osteoporosis and mutation of PLS3, however the underlying mechanism, as well as how PLS3 contributes to general bone health and maintenance, is not understood." (PMID 38089885, 2023). "The severity of clinical manifestations in OI does not appear to be directly associated with specific PLS3 variants, varying greatly from the absence of physical symptoms to severe early-onset osteoporosis and deformity." (PMID 37484945, 2023). "In the mean time, in transiliac bone biopsies from two patients with PLS3 mutation-induced osteoporosis, no osteoblasts or osteoclasts were detected and the erosion surface was reduced." (PMID 37484945, 2023). "Despite mounting evidence supporting the deficiency of PLS3 caused by pathogenic mutations will result in the phenotype of osteoporosis, whether decreased PLS3 level was also involved in the occurrence of osteoporosis in general population remains unknown." (PMID 35752817, 2022).
osteoporosis (continued). "Of note, unlike other patients with early-onset osteoporosis caused by pathological mutation of PLS3 genes, the proband exhibited the phenotype of scoliosis at 10 years old (Risser sign 0)." (PMID 35752817, 2022). "Genotype–phenotype correlations, as well as association between osteoporosis and PLS3 levels in individuals without pathogenic mutations, were also investigated in the present study." (PMID 35752817, 2022). "However, in bone diseases such as osteoporosis or osteogenesis imperfecta, PLS3 seems to play an important role." (PMID 33802838, 2021). "Because PLS3 mutations cause childhood-onset osteoporosis associated with low BMD, it has been further hypothesized that the bone-forming osteoblasts might be disturbed by PLS3 loss." (PMID 34023917, 2021). "History of fractures and previous osteoporosis medication for 15 subjects with a hemizygous/heterozygous PLS3 mutation and 13 mutation-negative subjects." (PMID 32655496, 2020). "Although PLS3 is ubiquitously expressed in several other tissues, no constant extra-skeletal manifestations are associated with PLS3 osteoporosis." (PMID 32655496, 2020). "This suggests that WNT1 and PLS3-mediated osteoporosis might have a similar mechanism of disease progression." (PMID 32733380, 2020). "Mutations in actin-bundling protein plastin 3 (PLS3) emerged as a cause of congenital osteoporosis, but neither the role of PLS3 in bone development nor the mechanisms underlying PLS3-dependent osteoporosis are understood." (PMID 32509377, 2020). "Mutations in plastin 3 resulted in osteoporosis in mice which signifies the role of plastin 3 in osteoblasts and not osteoclasts." (PMID 30248139, 2018). "However, it remains unclear whether osteoclasts are the most affected cell type and are responsible for the development of osteoporosis in the mice with whole-body deletion of Pls3." (PMID 38549711, 2024). "Furthermore, genotype–phenotype relationships in PLS3-related early-onset primary osteoporosis and the relationship between PLS3 levels and osteoporosis in subjects without PLS3 pathogenic mutations were investigated." (PMID 35752817, 2022). "Moreover, the association between PLS3 levels and osteoporosis in individuals without pathogenic mutations in PLS3 needs to be determined." (PMID 35752817, 2022). "No renal abnormality has previously been linked to WNT1 or PLS3 osteoporosis." (PMID 36157448, 2022). "In Pls3 knock-out mice, osteoporosis and decreased bone strength could be detected." (PMID 33802838, 2021). "Defects of plastin-3 in the organization of actin filament bundles in bone cells may interfere the necessary conversion of mechanical signals to biochemical signals in osteoblasts and osteoclasts, thereby leading to osteoporosis." (PMID 30405713, 2018). "Defective cell spreading of PLS3 KD cells on stiff substrates could be rescued by expression of wildtype PLS3, but not by expression of three PLS3 mutations that were identified in patients with early onset osteoporosis and that have aberrant actin-bundling activity." (PMID 38089885, 2023). "Given that the role of LRP5, PLS3, and WNT1 in the development of osteoporosis was only discovered 10–15 years ago, and the rarity of these pathogenic variants, their associated morbidity and prognosis are still largely undetermined." (PMID 37277619, 2023). "However, the mechanism of PLS3 mutation leading to osteoporosis is unknown, and its effective treatment strategies have not been established." (PMID 37083757, 2023). "Moreover, whether decreased PLS3 levels were also involved in osteoporosis among subjects without PLS3 pathogenic mutations remains unknown." (PMID 35752817, 2022). "However, the role of lipocalin-2 in WNT1 and PLS3 osteoporosis is unknown." (PMID 36157448, 2022). "The expression of PLS3 is of utmost interest in the context of several medical conditions, such as spinal muscular atrophy (SMA), osteoporosis, osteoarthritis as well as a large number of cancers." (PMID 34023917, 2021).
osteoporosis (continued). "The patient inherited the PLS3 deletion from his unaffected mother and the LRP5 variant from his father with spinal osteoporosis but no fractures." (PMID 38043102, 2024). "Individual PLS3 patients have been reported to have muscle hypotonia, but no systematic review of muscle involvement in PLS3 osteoporosis has been reported." (PMID 32655496, 2020). "Although both genes have been linked to monogenic forms of osteoporosis, COL1A2 deletions are rare and PLS3 duplications have not been described previously." (PMID 30042735, 2018). "Although studies have convincingly shown elevated osteoclast activity in a ubiquitous Pls3 knockout mouse model, multiple cell types may be involved as shown by the absence of osteoporosis in a mouse model with osteoclast-specific Pls3 knockout." (PMID 39273077, 2024). "Our observation that the osteopathogenic PLS3 mutants failed to rescue osteoblast spreading and adhesion, which is an important factor driving late osteoblast mineralization, further begins to elucidate how PLS3 contributes to bone health and by extension, to bone defects such as osteoporosis." (PMID 38089885, 2023).
spinal muscular atrophy (15 papers, 2012 to 2023). A motor neuron disease that affect the muscles, and characterized by muscle weakness and atrophy resulting from progressive degeneration and irreversible loss of the anterior horn cells in the spinal cord (i.e., lower motor neurons) and the brain stem nuclei. "Pls3 (Plastin 3) encodes an actin binding protein that reduced in a mouse model of spinal muscular atrophy, and its overexpression restored axonal outgrowth of motor neurons in SMA." (PMID 33362469, 2020). "The plastin 3 (PLS3) gene acts as a modifier of the clinical penetrance of autosomal recessive spinal muscular atrophy, caused by the homozygous deletion of the SMN1 gene." (PMID 23820649, 2013). "Improved endocytosis has also been proposed to account for the role of PLS3 as a protective modifier of spinal muscular atrophy." (PMID 37484945, 2023). "Instead in several neuromuscular disorders, such as spinal muscular atrophy (SMA), amyotrophic lateral sclerosis (ALS) and CHP1-associated ataxia, PLS3 overexpression acts as a protective modifier." (PMID 34023917, 2021). "For example, in Spinal Muscular Atrophy, the genes Plastin-3 (PLS3) and Coronin 1C (CORO1C) were identified as protective modifiers, unraveling impaired endocytosis as a rescue mechanism for the phenotype." (PMID 32671069, 2020). "Here, we examine the relationship between the motor neuron disease spinal muscular atrophy (SMA), which is caused by reduced levels of the survival of motor neuron (SMN) protein, and the actin-bundling protein Plastin 3 (PLS3)." (PMID 32938453, 2020). "On the other hand, studies on spinal muscular atrophy have evidenced that PLS3 partakes in formation of neuromuscular synapses and that its overexpression can salvage axonal defects in a SMA mouse model." (PMID 32655496, 2020). "PLS3 overexpression (OE) has been extensively demonstrated to be a protective modifier for the devastating neurodegenerative disorder spinal muscular atrophy (SMA) in humans and numerous SMA models." (PMID 31607845, 2019). "Plastin 3 (PLS3), a proven protective modifier of spinal muscular atrophy across species, is a remarkable example of the former, and thereby offers high potential as a cross-disease modifier." (PMID 31607845, 2019). "PLS3 has been shown to play a role in fundamental cellular processes, including cell migration, cell-cell contact and endocytosis, which further explain how PLS3 contributes to cancer metastasis, cardiovascular defects, and spinal muscular atrophy." (PMID 38089885, 2023). "Instead, when PLS3 is upregulated, it acts as a highly protective SMN-independent modifier in spinal muscular atrophy (SMA)." (PMID 34023917, 2021). "On the other hand, in spinal muscular atrophy (SMA), PLS3 gene is an age- and sex-specific modifier." (PMID 30405713, 2018). "Actin-binding protein plastin 3 (PLS-3) levels are reduced in spinal muscular atrophy (SMA), and transgenic reintroduction of PLS-3 rescues functional defects in SMA." (PMID 26843990, 2016). "Another study on spinal muscular atrophy (SMA) showed that PLS2 was able to perform the same role as PLS3 in motor axons, thereby substituting for PLS3, albeit less efficiently, while PLS1 showed no ability to rescue these defects even though PLS1 could also bind and bundle actin." (PMID 37484945, 2023).
colorectal cancer (13 papers, 2012 to 2025). A primary or metastatic malignant neoplasm that affects the colon or rectum. "A study in colorectal cancer cells states that PLS3 is a downstream target of Lamin A, which is a risk factor for this type of cancer." (PMID 34023917, 2021). "In the present study, we were able to detect KRAS, BRAF, CD133 and PLS3 mutations in cell suspension enriched for all CTCs populations and in the corresponding primary tumor of 52 patients with colorectal cancer." (PMID 25902072, 2015). "Previous studies have established PLS3 as a driver of aggressive progression in colorectal cancer, breast cancer, as well as other solid tumors." (PMID 41375083, 2025). "PLS3 is highly expressed during epithelial–mesenchymal transition (EMT) in circulating tumor cells (CTCs) in colorectal cancer." (PMID 34023917, 2021). "High PLS3 expression has been shown to have poor prognosis in pancreatic cancer, acute myeloid leukemia, gastric cancer, and colorectal cancer." (PMID 32599841, 2020). "Plastin 3 (PLS3) was recently described as a potential marker of breast and colorectal cancer CTCs, including those after EMT." (PMID 30634453, 2019). "In colorectal cancer, Plastin3 (PLS3) was identified as a marker for EMT-CTCs, helping to detect CTCs as this marker is not expressed in healthy blood cells." (PMID 27529216, 2016). "We have observed that biphenotypic CTCs-positive samples had increased expression of PLS3, which indicates that similarly to colorectal cancer, PLS3 is overexpressed in CTCs undergoing EMT and is a good marker with minimal expression in blood of healthy controls." (PMID 30634453, 2019). "The oncogenic role of PLS3 on EMT was also reported in colorectal cancer." (PMID 29610526, 2018). "Recent data show that apart from KRAS and BRAF mutations, mutations in genes related to colorectal cancer stem cells or cells that undergo EMT, such as CD133 and PLS3, might have therapy-predictive value and clinical significance." (PMID 25902072, 2015). "For example, the recent description of Plastin 3 as a hitherto unknown but important epithelial-mesenchymal transition (EMT) marker in colorectal cancer is illustrative." (PMID 24351672, 2013). "In colorectal cancer, Plastin-3 has been proposed but has not yet been validated as a robust marker." (PMID 34638450, 2021). "Elevated levels of PLS3 during EMT in CTCs negatively regulate expression levels of epithelial genes, and positively regulate the levels of mesenchymal genes and thereby increase the invasiveness of colorectal cancer." (PMID 34023917, 2021). "Similarly, high expression of PLS3 was significantly related to copy number gain of chr.Xq23 which is its genetic locus and promoted EMT through transforming growth factor (TGF)-β signaling in colorectal cancer cells." (PMID 35729213, 2022).
breast carcinoma (10 papers, 2016 to 2025). "Similarly, elevated PLS3 in CTCs serves as a biomarker for recurrence risk and unfavorable outcomes in breast cancer." (PMID 41375083, 2025). "Nevertheless, there have been a number of studies of PLS3 in other human cancers, including gastric, colorectal, and breast cancers, as well as cutaneous T-cell lymphoma and acute myeloid leukemia." (PMID 34348730, 2021). "The epithelial markers (CK18 and CK19) were expressed in all breast cancer cell lines, whereas the mesenchymal markers (PLS3, vimentin, and N-cadherin) were expressed mainly in the non-epithelial cell lines." (PMID 31947504, 2020). "Our results have shown that different EMT phenotypes of CTCs (epithelial, epithelial-mesenchymal and mesenchymal) can be distinguished in CTCs-EBF of early breast cancer using a panel of 7 genes (MGB1/HER2/CK19/CDH1/CDH2/VIM/PLS3) tested in qPCR." (PMID 30634453, 2019). "Ueo and colleagues observed PLS3 expression in circulating tumor cells of patients with breast cancer." (PMID 31717802, 2019). "In order to determine the variation, we have compared the level of general breast cancer markers (MGB1, HER2) and genes used for CTCs-EBF classification into EMT phenotypes (CK19, CDH1, VIM, CDH2, PLS3)." (PMID 30634453, 2019). "These included genes such as SCUBE3, MARCKSL1 and PGK1 in lung cancer, SOX4 and GNAS in breast cancer and hepatocellular carcinoma, HEG1 in hepatocellular carcinoma, PLS3 in pancreatic adenocarcinoma, FBN1 and SPARC in gastric cancer and CST1 in gastric cancer and breast cancer." (PMID 40430098, 2025). "Expression of VIM, CDH1, CDH2, PLS3, CXCR4, CD44 and NANOG have been found in healthy controls and the maximal expression levels of these genes were the threshold beyond which CTCs-EBF of breast cancer patients were considered positive." (PMID 30634453, 2019). "In this context, plastin-3, an actin-bundling protein not downregulated during EMT on CRC and breast cancer cells—and not expressed on leukocytes—might be a major advance." (PMID 27182774, 2016). "While proteins such as vimentin and Plastin 3 showed no notable changes, other EMT markers like Keratin 5 and E-Cadherin were affected, suggesting that although similar pathways may be involved, distinct proteins play central roles in breast cancer and NSCLC." (PMID 40301999, 2025).
osteogenesis imperfecta (10 papers, 2018 to 2025). Osteogenesis imperfecta (OI) comprises a heterogeneous group of genetic disorders characterized by increased bone fragility, low bone mass, and susceptibility to bone fractures with variable severity. "In the present study, a novel PLS3 variant in a nonconsanguineous family of a proband with X-linked OI was detected and potential link between this variant of plastin 3 and osteogenesis imperfecta was reviewed." (PMID 34946798, 2021). "The precise mechanisms by which plastin 3 causes osteogenesis imperfecta remain unclear, but recent advances have contributed to our understanding of bone development and the actin cytoskeleton." (PMID 33553175, 2020). "However, recently variants of the actin bundling protein plastin 3 have been identified as another source of osteogenesis imperfecta." (PMID 33553175, 2020). "PLS3-mediated osteogenesis imperfecta is an exciting new field of study with implications in the clinic as well as the fields of bone development and actin biochemistry." (PMID 33553175, 2020). "Bone mineral density quantitative trait locus 18 (BMND18, OMIM #300910), a recently described form of X-linked osteogenesis imperfecta (OI), is caused by loss-of-function mutations of the PLS3 gene." (PMID 30405713, 2018). "Bone mineral density quantitative trait locus 18 (BMND18, OMIM #300910) is a type of early-onset osteogenesis imperfecta (OI) caused by loss-of-function mutations in the PLS3 gene, which encodes plastin-3, a key protein in the formation of actin bundles throughout the cytoskeleton." (PMID 30405713, 2018). "The importance of well-regulated Ca2+ homeostasis for the proper function of PLS3 is underlined by several findings of disturbed Ca2+ regulation associated with loss of its functionality, shown in PLS3 rescue in SMA models or osteogenesis imperfecta (OI)-associated PLS3 mutations." (PMID 34023917, 2021).